TRPA1 (transient receptor potential cation channel subfamily A member 1)
Diseases named in the same sentence as TRPA1 in open-access papers (continued):
Sharing a sentence is not in itself a finding about the gene and the disease.
colitis (46 papers, 2010 to 2025). Inflammation of the colon. "It is intriguing that although both TRPV1 and TRPA1 mediate Ca2+ influx that initiates intracellular Ca2+ signaling in a similar manner, loss of function of TRPV1 and TRPA1 show opposite phenotypes in mouse models of experimental colitis." (PMID 36459135, 2023). "TRPA1 has also been reported to contribute to visceral pain-like behaviors in dextran sulfate sodium (DSS)-evoked colitis, an effect associated with upregulation of channel expression and responsiveness in DRG nociceptors." (PMID 35562920, 2022). "Our findings indicate that the TRPA1 channel contributes to colitis-associated mechanical hypersensitivity in somatic tissues, an effect associated with upregulation of TRPA1 expression and responsiveness in DRG nociceptors." (PMID 32451393, 2020). "Taken together, these data show that the mechanical hypersensitivity associated with DSS-induced colitis in both the abdominal and facial region is prevented by genetic deletion of TRPA1." (PMID 32451393, 2020). "Studies with Trpv1 and Trpa1 gene-deficient mice show contradictory data about their roles in colitis, most likely depending on the key pathomechanisms of the different colitis models." (PMID 32764237, 2020). "Taken together, these data show that DSS-induced colitis caused mechanical hypersensitivity in the abdominal and periorbital region and that blockade of TRPA1 with HC-030031 reversed the DSS-induced mechanical hypersensitivity in both regions." (PMID 32451393, 2020). "The implication of TRPA1 in colitis-associated somatic hypersensitivity is in line with a number of reports that attribute TRPA1 a role in visceral nociception and hyperalgesia." (PMID 32451393, 2020). "The current findings underpin this contention as they show that TRPA1 plays an essential mediator role in the somatic mechanical hyperalgesia associated with DSS-induced colonic inflammation." (PMID 32451393, 2020). "Pharmacological blockade or genetic deletion of TRPA1 prevented the colitis-associated mechanical hypersensitivity in the abdominal and facial skin areas although the severity of colitis remained unaltered." (PMID 32451393, 2020). "TRPA1 has been reported to contribute to the inflammation-induced pain and is also associated with experimental colitis in mice models." (PMID 31488616, 2019). "TRPA1 is expressed in a population of visceral nociceptors and it has been shown that pathological activation of TRPA1 induces neurogenic inflammation associated with irritable bowel syndrome and colitis, and the resultant inflammatory pain." (PMID 27854251, 2016). "Introduction of excess AITC into the murine colon induces colitis which is associated with an upregulation of TRPA1 and other factors of the intestinal nervous and immune systems." (PMID 21420431, 2011). "Additionally, in colitis-associated colon cancer, stimulation of TRPA1, TRPM2, and TRPV1 increases mitochondrial ROS and Zn2+ dysregulation, promoting apoptotic cell death, an effect mitigated by antioxidant treatment with Sambucus ebulus L." (PMID 40813985, 2025). "TRPA1 in immune cells has been linked to arthritis (neutrophils), anaphylaxis and atopic dermatitis (mast cells), atherosclerosis, renal injury, cardiac hypertrophy and inflammatory bowel disease (macrophages), and colitis (T cells)." (PMID 34768891, 2021). "Furthermore DSS-induced colitis is associated with sensitization of TRPA1 in the colon, which through release of substance P contributes to induction and maintenance of inflammation." (PMID 32451393, 2020). "Whether the ability of TRPA1 inhibition and deletion to reduce colitis-associated somatic mechanical hypersensitivity is related to the observed nominal reduction of colonic MPO activity requires further investigation." (PMID 32451393, 2020).
colitis (continued). "The mechanisms underlying the anti-inflammatory actions of TRPA1 in colitis can be explained by decreasing proinflammatory SP, NKA, NKB and NK1 receptor expression, as well as inhibiting the synthesis of inflammatory cytokines and chemokines presumably derived from macrophages." (PMID 25265225, 2014). "The role of TRPA1 in a colitis model was investigated using gene-deficient mice." (PMID 25265225, 2014). "TNBS-evoked colitis is associated with an upregulation of TRPA1 in DRG neurons supplying the colon, an effect that may involve neurotrophic factors formed under conditions of irritation and inflammation." (PMID 21420431, 2011). "For example, the co-involvement of TRPV4 and TRPA1 plays a role in several health conditions, including colitis, itch, respiratory injuries, and chronic cough." (PMID 40325821, 2025). "The researchers induced colitis-associated colon cancer in mice and showed that the expression levels of the three TRP channels (TRPA1, TRPM2, TRPV1) were overexpressed." (PMID 40813985, 2025). "Three channels TRPA1, TRPM2 and TRPV1 have been shown to influence apoptosis in mice with colitis-associated colon cancer (azoxymethane (AOM)/DSS model)." (PMID 38731999, 2024). "It was demonstrated that in a mouse model of DSS-induced colitis pretreated with TRPA1 antagonist HC-030031, TRPA1 agonist allyl isothiocyanate (AITC) induced visceral hypersensitivity mediated by colonic chemical stimulation." (PMID 38731999, 2024). "In TNBS-induced experimental colitis in mice, TRPA1 has been found to mediate mechanical hypersensitivity to colonic distension." (PMID 38731999, 2024). "Intraperitoneal and intrathecal administration of TRPV1 and TRPA1 antagonists exerts analgesic effects in a rat colitis model that emphasizes central nervous system mechanisms (Ref." (PMID 38659380, 2024). "As such, in TRPV1- and TRPA1-deficient mice, induced DSS colitis was significantly attenuated compared to wild-type animals." (PMID 38731999, 2024). "Despite the inconsistencies in findings over the last 2 decades, preclinical evidence and limited human studies have indicated the potential therapeutic efficacy of TRPV1 and TRPA1 antagonists in treating colitis and visceral hypersensitivity." (PMID 39022308, 2024). "The protective role of TRPA1 in DSS colitis was demonstrated based on histological evaluation and confirmed by TRPA1-mediated suppression of pro-inflammatory neuropeptides and cytokines." (PMID 38731999, 2024). "In an animal study, mice with experimental colitis exhibited increased TRPA1-mediated release of colonic neuropeptides, whereas symptoms were reduced after TRPA1 inhibition by antagonists or gene deletions (Ref." (PMID 38659380, 2024). "Dextran sulfate sodium (DSS) treatment caused mechanical hypersensitivity in the abdominal and facial skin of colitis mice by increasing TRPA1 expression in cultured DRG neurons and selectively enhanced currents evoked by the TRPA1 agonist." (PMID 36910013, 2023). "A previous report indicated that the blockade of receptor channels such as TRPV1 and TRPA1 on nociceptive sensory neurons was shown to attenuate experimental colitis by suppressing the release of GRP and SP." (PMID 36910013, 2023). "TRPA1 is protective in a T-cell-mediated colitis model by inhibiting the TRPV1 activity in CD4+ T cells." (PMID 36875034, 2023). "As a mechanosensor, activation of TRPA1 is thought to be a factor in the generation of afferent mechanical hypersensitivity in models of colitis." (PMID 37039840, 2023). "This functional difference is also reflected by a TRPV1-mediated promotion but a TRPA1-mediated inhibition of experimental colitis in mice." (PMID 36459135, 2023). "Though CPZ has been employed as a strategy to ameliorate colitis related pain, its physiological effects on gut health and involvement of its key targets (TRPA1/TRPV1 sensory neurons) still remains elusive." (PMID 36076974, 2022).
colitis (continued). "In the rodent model of dextran sodium sulfate (DSS)-induced colitis, neuronal TRPA1 sensitization in the colon resulted in SP release that contributes to inflammation." (PMID 36076974, 2022). "In an experimental model of TNBS-evoked colitis, the inhibition, or genetic deletion, of TRPA1 reduced the inflammatory process by reducing colonic neuropeptide release (substance P and CGRP) from gut extrinsic sensory neurons." (PMID 35562920, 2022). "Cannabichromene, a cannabinoid TRPA1, reduced NO production by macrophages and attenuated colitis of murine." (PMID 34500744, 2021). "In other organs, the TRPA1 agonist, cannabichromene, exerts an anti-inflammatory response in activated macrophages by inhibiting nitric oxide production to ameliorate murine colitis." (PMID 33810314, 2021). "Using a murine DDS-induced colitis model, TRPA1 was shown to be upregulated in DDS-treated mice and human IBD patient samples and was expressed in interstitial and infiltrating macrophages, respectively." (PMID 34768891, 2021). "The present study investigated the role of TRPA1 in colitis-evoked mechanical hypersensitivity at the somatic level." (PMID 32451393, 2020). "Taken together, these data show that DSS treatment for 7 days induced colitis which remained unaffected by TRPA1 blockade with HC-030031." (PMID 32451393, 2020). "First, genetic deletion of TRPA1 prevented DSS-induced colitis from inducing mechanical hypersensitivity in both the abdominal and periorbital skin." (PMID 32451393, 2020). "Second, the selective TRPA1 antagonist HC-030031 inhibited the mechanical hypersensitivity that had developed after induction of colitis, and this observation was also made in both the abdominal and periorbital skin." (PMID 32451393, 2020). "Transient receptor potential ankyrin 1 (TRPA1) has been reported to contribute to visceral pain-like behavior in dextran sulfate sodium (DSS)-evoked colitis." (PMID 32451393, 2020). "The DSS-induced model of colitis has also shown contrasting results, with TRPA1 genetic deletion or treatment with antagonists increasing disease severity in some cases, but alleviating disease severity in others." (PMID 33193423, 2020). "In animal studies, mice with experimental colitis exhibited an increased TRPA1-mediated colonic neuropeptide release, while the experimental colitis appeared to be less severe after the inhibition of TRPA1 by the antagonist or genetic depletion." (PMID 32153564, 2020). "Whilst considering the highly co-expressive nature of TRPV1 and TRPA1 in colonic afferents, it is interesting to shed light on the interaction between TRPV1 and TRPA1 in colitis." (PMID 32153564, 2020). "We therefore conclude that it is primarily the function of TRPA1 which, relative to TRPV1, is upregulated in DRG neurons under conditions of colitis, although the somatic vs. visceral projection of TRPA1-hyperresponsive DRG neurons awaits to be analyzed." (PMID 32451393, 2020). "An implication of TRPA1 is evident from the observation that DSS-induced colitis is reduced by genetic deletion and pharmacologic blockade of TRPA129." (PMID 32451393, 2020). "The protective role of TRPA1 has also been described in the Il10−/−-induced spontaneous colitis model." (PMID 32764237, 2020). "TRPV1 and TRPA1 concert has been further investigated in acute colitis and visceral hypersensitivity model, where the blockade of both channels reduced visceromotor responses when compared to a single channel inhibition." (PMID 31197115, 2019). "Accordingly, colitis-induced mechanical hypersensitivity was reduced both in knockout TRPA1 mice and in wild type animals after administration of TRPA1 channel antagonists." (PMID 31370176, 2019). "The TRPA1 agonist TNBS (2,4,6-trinitrobenzene-sulfonic-acid), used for induction of colitis, caused IBD-like symptoms in mice due to a release of SP and CGRP." (PMID 31892361, 2019).
colitis (continued). "The authors propose a protective role of TRPA1 since in a murine model for colitis the disease activity index and the histological score were lower in TRPA1 expressing mice than in the knockout mice after 10 days of dextran-sulfate treatment." (PMID 31892361, 2019). "TNBS induces similar severe acute colitis in wildtype and Trpv1−/−, but reduced inflammation in Trpa1−/− mice or wildtype animals treated with the TRPA1 antagonist HC-030031." (PMID 30935063, 2019). "The protective anti-inflammatory effects of TRPA1 were recently demonstrated in mouse model of colitis, with TRPA1 KO mice having a significantly higher ‘Disease Activity Index’ and levels of pro-inflammatory neuropeptides and cytokines in the distal colon." (PMID 30974795, 2019). "Pharmacological blocking of TRPA1 attenuated chronic colitis through inhibition of neuropeptide release." (PMID 29467763, 2018). "Since macrophages are major producers of TNF-α and activation of TRPA1 was able to impair the expression of TNF-α in distal colon homogenates during colitis, it is likely that TRPA1 in macrophages mediated the anti-colitogenic effect." (PMID 29467763, 2018). "Data on the function of TRPA1 activation in experimental colitis are in fact contradictory, it has been reported to be proinflammatory, antiinflammatory or without any effect." (PMID 25265225, 2014). "Protective role of TRPA1 was clearly demonstrated in DSS colitis based on the Disease Activity Index and histological score and supported by the TRPA1-mediated downregulation of proinflammatory neuropeptides and cytokines." (PMID 25265225, 2014). "TRPA1 is upregulated in colitis and its activation exerts protective roles by decreasing the expressions of several proinflammatory neuropeptides, cytokines and chemokines." (PMID 25265225, 2014). "Regarding the mechanisms of the TRPA1-mediated antiinflammatory function in the DSS-induced murine colitis, we have presented evidence for the decreased NK1 receptor expression in the wild-type animals compared to the knockouts." (PMID 25265225, 2014). "TRPA1 is upregulated in experimental colitis and deletion of TRPA1 expression in a mouse gene “knocke-out” model reduced colitis-induced mechanical hypersensitivity." (PMID 22619712, 2012). "TRPA1 is up-regulated in colonic afferent DRGs after colitis induction, and treatment with TRPA1 antisense oligodeoxynucleotides or pharmacological blockage of TRPA1 suppresses colitis-induced hyperalgesia." (PMID 24288041, 2011). "TRPA1 agonists cause greater mechanical hypersensitivity in afferents from animals with acute TNBS-induced colitis compared with untreated mice, indicating an enhanced role for TRPA1 during inflammation." (PMID 27713376, 2010). "Notably, in the colon, mechanical hypersensitivity induced by TRPA1 agonists increased in afferents of mice with chemically induced colitis." (PMID 39022308, 2024). "Thus, while neuronal TRPA1 enhances acute inflammation, TRPA1 in CD4+ T cells reduces the severity of chronic T-cell-mediated colitis, confirming the protective role of TRPA1 in inflammation." (PMID 38731999, 2024). "TRPA1 is reported to be a major mediator of the TNBS-induced colitis." (PMID 36459135, 2023). "Genetic ablation of TRPV1 or TRPA1 significantly attenuates the severity of colitis." (PMID 36459135, 2023). "Moreover, it has been reported that the TRPA1 agonist cannabinoid reduces INF-γ in macrophages by inhibiting nitric oxide (NO) production to ameliorate colitis in mice." (PMID 36875034, 2023). "In animal models of colitis, TRPA1 has an inconsistent role inflammation." (PMID 33193423, 2020). "Our current data furthermore demonstrate that TRPA1 is an important signaling factor in colitis-associated hyperalgesia at the primary sensory neuron level because the severity of colitis was not affected by TRPA1 blockade or deletion." (PMID 32451393, 2020). "Further support showed that TRPA1 activation reduced the level of TNF-α in colitis." (PMID 32153564, 2020).
colitis (continued). "Trpa1 and Trpv1 gene deletion decreased dextran sulfate sodium (DSS)-induced colitis severity, as well as Il10−/−-induced spontaneous colitis in Trpv1-deficient mice, whereas Trpv1-deficient mice exhibited more severe colitis in the dinitrobenzene sulfonic acid (DNBS)-induced model." (PMID 32764237, 2020). "In order to further elucidate the contribution of TRPA1 to somatic pain hypersensitivity in mice with DSS-induced colitis, we assessed the sensitivity of abdominal and periorbital regions to mechanical stimuli in Trpa1+/+ and Trpa1−/− mice following DSS treatment." (PMID 32451393, 2020). "Similarly, TRPA1 has also been found to be upregulated in the intestine of mouse models and human subjects with colitis, ulcerative colitis and Crohn’s disease." (PMID 32947778, 2020). "In order to test whether the reduction of sensitivity to mechanical stimuli by blockade or deletion of TRPA1 is related to a change of DSS-induced colitis, we tested the effect of HC-030031 and TRPA1 deletion also on colitis-related parameters." (PMID 32451393, 2020). "Similarly, the levels of TRPV1 and TRPA1 messenger RNA (mRNA) in mice were upregulated in mustard oil (MO)-induced colitis within 6 h but decreased 24- and 72-h after MO-injection." (PMID 32153564, 2020). "Similarly, colitis in mice was attenuated by capsazepine due to a desensitisation of TRPA1 or to the reduction of neuropeptides release such as SP and CGRP." (PMID 31197115, 2019). "Likewise, TRPA1 is unequivocally overexpressed in models of colitis in mice and in colon biopsies obtained from human UC and CD patients." (PMID 31652951, 2019). "However, they described that TRPV1 and TRPA1 gene deletion decreased colitis severity and the upregulation of SP-positive nerve fibers without influencing protective CGRP-positive nerves." (PMID 30935063, 2019). "Moreover, intraperitoneal co-injection of a TRPV1 inhibitor and a TRPA1 antagonist in a mouse model of experimental colitis results in a substantial reduction of VH compared to injection of the antagonists separately, suggesting a synergistic effect." (PMID 31652951, 2019). "Upregulation of TRPA1 has been demonstrated in experimental colitis." (PMID 31370176, 2019). "Moreover, both intraperitoneal and intrathecal administrations of TRPV1 and TRPA1 antagonists exerted analgesic actions in rat colitis models highlighting central nervous system mechanisms." (PMID 30935063, 2019). "Similarly, previous studies demonstrated that the TRPA1-agonists isothiocyanate and formalin also induce colitis in rodents." (PMID 31892361, 2019). "On the contrary, selective TRPA1 agonists relieved colitis and abdominal pain in murine models." (PMID 31197115, 2019). "However, in similar models of colitis, TRPA1 channels are shown to contribute to disease pathology, with TRPA1 antagonists being designed and trialed for treatment of inflammation and pain." (PMID 28346371, 2017). "To resolve this discrepancy, we sought to determine whether TRPA1 is also involved in colitis protection through unknown, off-target effects of CPZ." (PMID 27356469, 2016). "However, both DSS-induced and TNBS-induced colitis were significantly reduced in TRPA1 KO mice or WT mice treated with the TRPA1 antagonist HC-030031." (PMID 25640188, 2015). "Furthermore, intrathecal injection of an antisense oligodeoxynucleotide, to down regulate TRPA1 expression, suppresses the colitis-induced hyperalgesia to nociceptive CRD and intracolonic mustard oil in rats studied 8 days post-TNBS." (PMID 27713376, 2010). "Thus, TRPA1 in CD4+ T-cells appears to reduce the severity of T-cell-mediated colitis." (PMID 37039840, 2023). "In addition, TRPA1 and SP have long been associated with various disorders, including skin inflammation, neuropathic pain, and colitis; however, their connection to GERAHR has not been elucidated." (PMID 35586690, 2022). "Therefore, pain control by suppressing TRPV1 and TRPA1 proteins could be a promising target in colitis management." (PMID 35269566, 2022).